NEU1 (neuraminidase 1)
Diseases named in the same sentence as NEU1 in open-access papers (continued):
Sharing a sentence is not in itself a finding about the gene and the disease.
pancreatic cancer (12 papers, 2014 to 2024). "Oseltamivir inhibits NEU-1 activity and suppresses intrinsic signaling for the survival of human pancreatic cancer cells with chemoresistance." (PMID 39194692, 2024). "Oseltamivir is known to disable human pancreatic cancer (PANC1) cell survival by inhibiting NEU-1 (sialidase) activity and its intrinsic signaling." (PMID 38469236, 2024). "In pancreatic cancer cells, NEU1 removes sialic acids from EGFR, leading to EGFR dimerization and the activation of pro-survival pathways." (PMID 39194692, 2024). "We have preliminary data on OP analogs on pancreatic cancer cells that certain analogs are an order of 105 magnitudes more effective at inhibiting Neu-1 than the parental OP." (PMID 35892853, 2022). "O’Shea’s team showed that oseltamivir inhibits the NEU-1 activity and suppresses the intrinsic signaling that promotes the cell survival of human pancreatic cancer (PANC1) cells that are resistant to drug therapy." (PMID 36230790, 2022). "The data suggest that targeting mammalian neuraminidase-1 on pancreatic cancer cells with these repurposed drugs is crucial for modulating cell proliferation, invasion, clonogenicity, and migration." (PMID 35326525, 2022). "Haxho and coworkers have reported that NEU-1 plays a key role in the sialidase-mediated tumorigenesis in pancreatic cancer." (PMID 36230790, 2022). "The implication of NEU-1 in other cancer types has also been shown notably in the development of pancreatic carcinoma and breast cancer." (PMID 36230790, 2022). "In pancreatic cancer, enhanced NEU1 expression was involved in MMP9-EGFR signaling, and promoted cancer progression and metastasis." (PMID 32164705, 2020). "Based on preclinical data using a mouse model of human pancreatic cancer, we proposed that Neu1 is a novel alternate anti-cancer target in restraining tumor neovascularization, growth, metastases, and macrophage-mediated tumorigenesis." (PMID 27029067, 2016). "Neu1 inhibition by oseltamivir phosphate has been shown to specifically increase E-cadherin expression and to decrease N-cadherin expression in pancreatic cancer, triple-negative breast cancer and in ovarian tumor models." (PMID 27029067, 2016). "In the present study, we identified a novel treatment approach targeting Neu-1 that is hypothesized to ablate these compensatory effects of pancreatic cancer." (PMID 35892853, 2022). "It is noteworthy that others have found a dramatic increase in the activity of MMP-9 in gemcitabine-resistant pancreatic cancer cells, which fits well within our molecular signaling platform of Neu1-MMP-9 cross-talk in regulating ligand-induced receptor tyrosine kinases." (PMID 26932374, 2014). "Furthermore, given the role of α5β1 in protecting against apoptosis and promoting growth through the PI3K/Akt pathway, Neu-1 was found to promote cell proliferation and induce apoptosis by inhibiting the Akt pathway, which warrants further investigation for pancreatic cancer cell lines." (PMID 35326525, 2022). "However, a separate study indicates that Neu1 facilitates EGFR signaling in pancreatic cancer and thus could have a tumor promoting effect." (PMID 25184537, 2014). "We have reported that therapeutic targeting of Neu-1 with OP and ASA disables this intrinsic receptor signaling platform for cancer cell survival in human pancreatic cancer with acquired chemoresistance." (PMID 35326525, 2022). "Additionally, the therapeutic targeting of Neu-1 with oseltamivir and aspirin with gemcitabine (GEM) treatment significantly disrupts critical signaling mechanisms, tumor progression, and metastasis in a preclinical mouse model of human pancreatic cancer." (PMID 37894470, 2023).
Insulin resistance (11 papers, 2019 to 2025). Increased resistance towards insulin, that is, diminished effectiveness of insulin in reducing blood glucose levels. "One study found that Olanzapine, an antipsychotic agent associated with insulin resistance, induced Neu3 activity on the cell surface, which surprisingly inhibited Neu1 activity." (PMID 39128726, 2024). "This study’s results confirm the findings from others that Neu-1 has a significant role in IR regulation, as mice with a Neu-1 deficiency develop hyperglycemia and insulin resistance twice as fast as the wild-type when exposed to a high-fat diet." (PMID 36831374, 2023). "Murine hepatocytes treated with EDPs in the context of nonalcoholic steatohepatitis linked to insulin resistance had decreased hepatic growth factor receptor (HGFR) phosphorylation as a consequence of NEU1-mediated HGFR desialylation." (PMID 35479093, 2022). "Mice deficient in Neu1 rapidly developed glucose intolerance and insulin resistance after being fed with HFD." (PMID 31521172, 2019). "Ambroxol pharmacologically reverses the abnormalities of insulin resistance and glucose metabolism in mice through the acute pharmacological induction of NEU1 activation, corroborating that NEU1 can serve as a drug target in T2DM." (PMID 39194692, 2024). "Previous studies have highlighted Neu-1’s role in tumorigenesis, inflammation, and insulin resistance, all of which are hallmarks of cancer progression and metastasis." (PMID 38534324, 2024). "NEU1 engages in the regulation of insulin signaling in multiple ways, including facilitating the initiation of insulin signaling, reversing insulin resistance, and cross-talking with MMP9." (PMID 39194692, 2024). "The authors concluded that acacetin reverses insulin resistance in obese model mice by regulating the Treg/Th17 cell balance through a miR-23b-3p – NEU1 axis." (PMID 35479093, 2022). "Therefore, inhibition of Neu1 activity and EDP binding to elastin-binding protein can reduce insulin resistance caused by EDPs." (PMID 39128726, 2024). "The high expression of NEU1 predictably reverses insulin resistance." (PMID 39194692, 2024). "Emerging evidence supports the proposition that NEU1 can serve as a potential drug target for type 2 diabetes, wherein its activation may help rectify insulin resistance and check aberrations in glucose metabolism." (PMID 39194692, 2024). "However, the increase of NEU1 activity in insulin target tissues reversed insulin resistance and glucose intolerance." (PMID 31521172, 2019). "All above, it is possible to view NEU1 as a new therapeutic target in insulin resistance." (PMID 31521172, 2019). "In these same studies, pharmacologic upregulation of NEU1 expression and activity with ambroxol in mice led to desialylation of the IR, increased IR Tyr phosphorylation and Akt signaling, and improved glucose tolerance and insulin resistance in mice exposed to a HFD." (PMID 35479093, 2022). "The role of NEU-1 is notably associated with signal transduction through the ERC, but also to the biological effects that are induced by the EDPs on several pathologies as cancers, atherosclerosis, thrombosis, insulin resistance and non-alcoholic steatohepatitis." (PMID 36230790, 2022). "Overexpression of NEU1 in HEK293 cells increased IR desialylation and dimerization, and NEU1 overexpression in human HepG2 liver cells reversed palmitate-induced insulin resistance." (PMID 35479093, 2022). "Animal studies highlight Neu-1’s role in obesity, insulin resistance (IRES), and non-alcoholic fatty liver disease (NAFLD) by regulating adipocyte hypertrophy, insulin receptor (IR) signaling, and hepatic lipid metabolism." (PMID 39861189, 2025). "In a mouse model of obesity-induced insulin resistance, the percentages of CD4+FoxP3+ Treg cells and NEU1 levels were decreased, while the percentages of CD4+Th17+ cells and the levels of the NEU1-targeting microRNA, miR-23b-3p, were increased, all compared with nonobese controls." (PMID 35479093, 2022).
Insulin resistance (continued). "The activation of NEU-1 is required for elastogenesis and signal transduction through this receptor, and this is responsible for the biological effects that are mediated by the elastin-derived peptides (EDP) on obesity, insulin resistance and non-alcoholic fatty liver diseases." (PMID 36230790, 2022).
cardiac hypertrophy (10 papers, 2020 to 2025). "Our research extended these observations, revealing an association between increased NEU1 protein levels induced by sotorasib and the development of cardiac hypertrophy." (PMID 40221400, 2025). "Previous studies have underscored strong associations between NEU1 and oxidative stress, cardiac hypertrophy, and cardiac dysfunction." (PMID 40221400, 2025). "Cardiomyocyte-specific NEU1 deficiency can restore cardiac function, thereby improving the conditions of myocardial hypertrophy and interstitial fibrosis." (PMID 39194692, 2024). "Cardiomyocyte-specific NEU1 deficiency restored cardiac function, cardiac hypertrophy, and myocardial interstitial fibrosis." (PMID 35548408, 2022). "In an experimental model of cardiac hypertrophy and in patients with hypertrophic cardiomyopathy, NEU1 was found to be highly expressed in hypertrophic hearts." (PMID 39194692, 2024). "Overexpression of neuraminidase 1 (NEU1) is observed in cardiomyocytes, invading monocytes, and leads to inflammation, heart hypertrophy, and heart failure in ischemia-reperfusion heart injury in mice." (PMID 38672493, 2024). "Elsewhere, C-09, a compound that forms hydrogen bonds with NEU1, was experimentally shown to improve pathological cardiac hypertrophy by targeting NEU1." (PMID 39194692, 2024). "NEU1 is a key driver of myocardial hypertrophy, and anti-influenza drugs zanamivir and oseltamivir (viral NEU inhibitors) can significantly alleviate myocardial hypertrophy." (PMID 35548408, 2022). "In the human hypertrophic cardiomyopathy or rodent myocardial hypertrophy model, NEU1 was significantly increased, and targeted inhibition of NEU1 expression effectively prevented the development of cardiac hypertrophy and remodeling." (PMID 35548408, 2022). "What is more, a recently published study identified that NEU1 acted as a crucial driver in cardiac hypertrophy by interplaying with transcriptional factor GATA4." (PMID 34977042, 2021). "In addition, upregulation of NEU1 after ischemia/reperfusion (I/R) promotes heart failure by promoting monocyte/macrophage inflammation and enhancing myocardial hypertrophy." (PMID 34869700, 2021). "The overexpression of neuraminidase 1 in hypertrophic cardiomyocytes and its interaction with the nuclear GATA4 gene promotes the development of cardiac hypertrophy in mice." (PMID 38672493, 2024). "We have previously shown that NEU1 translocated to the nucleus to bind with transcriptional factors GATA4, promoting cardiac hypertrophy and remodeling." (PMID 36973294, 2023).
asthma (9 papers, 2015 to 2024). "Th2-mediated airway inflammation was caused by CD44–HA interactions through Neu1-meidated desialylation in the airway of asthma mouse model." (PMID 38500102, 2024). "Although some studies have linked NEU1 gene with asthma via Th2-mediated airway inflammation, and it is known that the Th2 pathway is also important for eczema, based on our knowledge, no study has so far spotted its role in eczema." (PMID 26199674, 2015). "NEU1 is negatively associated with type 1 diabetes, diffuse diseases of connective tissue, and asthma, and its increased expression may reduce the risk of these diseases." (PMID 38997544, 2024). "Previous reports demonstrated that Neu1-meidated HA-CD44 binding play an important role in asthma, while HA-CD44 binding is also correlated with tumorigenesis or metastasis in lung cancer." (PMID 38500102, 2024). "We found that an increase in NEU1 expression, in addition to potentially reducing the risk of SLE, also lowers the risk of several other diseases, such as Type 1 diabetes, asthma, and diffuse diseases of connective tissue." (PMID 38997544, 2024). "Although we focused on the potential implications of CHIT1 inhibition in the context of asthma severity and airway remodeling, other enzymes hold therapeutic promise for glycosylation regulation, such as galectins, NEU1, and FUT2." (PMID 38785919, 2024). "It has been reported that Neu1 was upregulated in airway smooth muscle cells from patients with asthma, and inhibition of Neu1 reduced airway hyperresponsiveness in mice with asthma." (PMID 38500102, 2024). "Similar to what we observed in BAT3, NEU1 had decreased DNA methylation in cg05550349 (exon 3) after HRVI in children with asthma compared to controls." (PMID 30485264, 2018). "Of these 16 modified CpGs, 4 were localized on chromosome 6 (chr6p21.32-p21.33), and 2 of the 16 identified CpGs, BAT3 and NEU1, showed a correlation between DNA and mRNA values, and were previously investigated in the context of asthma and HRVI." (PMID 30485264, 2018). "Katoh and colleagues demonstrate that the accumulation of Th2 cells was reduced in the airway of SM/J NEU1-knockout mice using a Dermatophagoides farinae -induced model of asthma." (PMID 30485264, 2018). "DNA methylation analysis of primary nasal epithelial cells from children with or without asthma implicated NEU1 in the host immune response to human rhinovirus-16 infection." (PMID 35479093, 2022). "It was hypothesized that the identified downregulation of M6PR, TPP1, GLB1, NEU1, ACP2, LAMP1 and HGSNAT leads to disorders of lysosome function, which results in asthma by causing T-cell dysfunction." (PMID 25633562, 2015). "In recent years, numerous evidence has suggested that human NEU1 is also involved in the pathogenesis of various respiratory diseases, including lung infection, chronic obstructive pulmonary disease (COPD), asthma, and pulmonary fibrosis." (PMID 38500102, 2024). "In this review, we used keywords such as “Neu1”, “sialidase 1”, “respiratory disease”, “lung infection”, “COPD”, “asthma”, and “pulmonary fibrosis” to identify relevant articles on PubMed." (PMID 38500102, 2024). "Neu1 was upregulated in lung tissues of patients with COPD and asthma, suggesting that it may play a role in the development of these diseases." (PMID 38500102, 2024). "The enzymatic activity of NEU1 increases the signaling of T helper 2 (TH2) cells and was found to infiltrate and accumulate in the airways and inflamed areas in murine models during acute asthma attacks and children with asthma after viral infection." (PMID 37415598, 2023). "Compared with non-asthmatic controls, NEU1 mRNA levels were decreased in asthma subjects with rhinovirus-16 infection, and a positive correlation between NEU1 gene methylation and NEU1 transcript levels was observed." (PMID 35479093, 2022).
asthma (continued). "Stringent application of minimum-change-filtering and verification of identified DNA methylation and mRNA expression findings allowed identification of asthma-specific target genes like BAT3 and NEU1 and offers potential new avenues for patient stratification and personalized therapy." (PMID 30485264, 2018).
heart failure (9 papers, 2020 to 2024). Inability of the heart to pump blood at an adequate rate to meet tissue metabolic requirements. "Overall, the upregulation of NEU1 following I/R drives heart failure by promoting inflammation mediated by infiltrating monocytes/macrophages, promoting cardiomyocyte hypertrophy, and impairing gap junction function." (PMID 39194692, 2024). "Studies have shown that NEU1 upregulation in infiltrating cardiac monocytes and macrophages leads to heart failure after ischemia-reperfusion by promoting inflammation." (PMID 35548408, 2022). "It was recently shown that NEU1, upregulated early in the ischemic and infarcted area, significantly contributes to the development of heart failure following ischemia/reperfusion (I/R) injury in mice with a cardiomyocyte-specific overexpression of NEU1." (PMID 36009856, 2022). "Here, we report that NEU1 in the hematopoietic system plays a role in heart failure after I/R since hNEU1-BM transplanted into WT mice was associated with better LV function after I/R." (PMID 32975669, 2020). "Our study showed that the relative amounts of TFAM and mtDNA decreased significantly in the mouse heart failure model after MI, and clearly proved that NEU1 inhibition can limit the decline of mtDNA levels and keep it at a normal level in the heart tissue of MI mice." (PMID 35548408, 2022). "In addition to regulating oxidative stress, upregulation of NEU1 can promote the inflammatory invasion of monocytes/macrophages, enhance cardiomyocyte hypertrophy, weaken the function of gap junctions, and lead to heart failure." (PMID 35002528, 2022). "Here, we hypothesize that the upregulation of NEU1 in hearts exposed to I/R may promote inflammation, arrhythmias, adverse cardiac remodelling, and heart failure." (PMID 32975669, 2020). "Therefore, cardiomyocyte-specific NEU1 may provide an alternative treatment strategy for heart failure post-MI." (PMID 35548408, 2022). "Existing NEU1 inhibitors (antiviral drugs such as zanamivir and oseltamivir) have good safety and pharmacokinetic properties and may be used to ameliorate mitochondrial metabolism and oxidative stress in myocardial infarction or heart failure." (PMID 35548408, 2022). "In addition, in ischemia/reperfusion mice model, NEU1 expression and activity were increased in cardiomyocytes as well as in invading monocytic cells, contributing to stronger inflammation and eventually heart failure." (PMID 34977042, 2021). "The upregulation of NEU1 after I/R contributes to heart failure by promoting inflammation in invading monocytes/macrophages, enhancing cardiomyocyte hypertrophy, and impairing gap junction function, suggesting that systemic NEU1 inhibition may reduce heart failure after I/R." (PMID 32975669, 2020). "Taken together, these data point to an adverse effect of an activated NEU1/β-GAL/PPCA complex on the heart after I/R and suggest that targeting this complex may lead to a novel therapeutic strategy to reduce adverse remodelling and heart failure after MI." (PMID 32975669, 2020). "Of note, in contrast to the C57BL/6 genetic background of hNEU1 mice, I/R did not lead to heart failure in WT mice of the FVB/N genetic background in which NEU1 and NEU3 transgenes were generated and therefore a potential benefit of NEU3 overexpression could not be assessed." (PMID 32975669, 2020). "Therefore, we investigated the roles of NEU1 and NEU3 in the heart exposed to I/R and observed that increased NEU1 expression and activation is associated with high inflammation and an increased risk of heart failure, while NEU3 had no such effects." (PMID 32975669, 2020).